HJURP (Holliday junction recognition protein)
Diseases named in the same sentence as HJURP in open-access papers (continued):
Sharing a sentence is not in itself a finding about the gene and the disease.
renal carcinoma (1 paper, 2023). A carcinoma arising from the epithelium of the renal parenchyma or the renal pelvis. "A previous study had shown that HJURP silencing inhibited the proliferation of human renal cancer CAKI-1 cells, arresting them in G2/M phase, and diminished their migratory capacity by inhibiting EMT and downregulating p-AKT and p-GSK3β." (PMID 37025176, 2023). "While these studies suggested that HJURP plays a pro-oncogenic role, HJURP may also exert antitumoral properties in renal cancer." (PMID 37025176, 2023). "In addition, there is evidence that HJURP promotes immune escape in renal cancer, an interesting phenomenon whose driving mechanism deserves also further enquiry." (PMID 37025176, 2023). "Furthermore, survival analysis showed that overall survival was lower in renal cancer patients with high HJURP expression." (PMID 37025176, 2023).
Sepsis (1 paper, 2025). Sepsis is defined as life-threatening organ dysfunction caused by a dysregulated host response to infection. "Conversely, the expression of CCNB2, HJURP, KREMEN1, LILRA5, and SIPA1L2 was significantly higher in the sepsis group (P < 0.05)." (PMID 40129981, 2025).
small cell lung carcinoma (1 paper, 2022). Small cell lung cancer (SCLC) is a highly aggressive malignant neoplasm, accounting for 10-15% of lung cancer cases, characterized byrapid growth, and early metastasis. "KEGG analysis indicated that the main pathways regulated by HJURP were cell cycle, pathways in cancer, cellular senescence, small cell lung cancer and DNA replication." (PMID 35173547, 2022).
synovial sarcoma (1 paper, 2023). "Data on HJURP expression in human bone and soft tissue tumors remains limited, as only one study currently exists that investigated its levels in 58 synovial sarcoma (SS) cases." (PMID 37958340, 2023).
thymoma (1 paper, 2022). A neoplasm arising from the epithelial cells of the thymus. "Specifically, these three patients had putative copy number alterations (deep deletions, homodeleted HJURP in all cases) whereas one of them with a type AB thymoma had five additional missense mutations of unknown significance." (PMID 35955489, 2022). "On the other hand, cBioPortal identified the presence of HJURP alterations in 3/124 patients (2 type AB and 1 type A thymoma patients) from the TCGA TETs cohort." (PMID 35955489, 2022).
cancer (62 papers, 2009 to 2025). A tumor composed of atypical neoplastic, often pleomorphic cells that invade other tissues. "The histone chaperone Holliday Junction Recognition Protein (HJURP) has been associated with multiple types of cancers, but its role in GC is not yet fully understood." (PMID 40290723, 2025). "HJURP is considered an oncogene as its overexpression has been associated with cancers including breast cancer, lung cancer, ovarian cancer, glioblastoma, hepatocellular carcinoma, colorectal cancer, and pancreatic cancer." (PMID 41370334, 2025). "In this article, we summarize the available data on the structure, localization, and molecular functions of HJURP and review its pathogenic role in human cancers, addressing its potential as a diagnostic, prognostic, and therapeutic cancer marker." (PMID 37025176, 2023). "Previous studied reported that several key proteins and signaling pathways were involved in HJURP-associated cancer progression." (PMID 35965590, 2022). "Alternatively, our results indicated that HJURP expression was associated with immune cell infiltration in a variety of cancers." (PMID 36460821, 2022). "Our results showed that HJURP expression abnormally elevated in the pan-cancer cohort, which was significantly associated with poorer clinical prognosis." (PMID 36460821, 2022). "Since similar associations of CENP-A and HJURP with tumor stage have been previously reported in a variety of carcinomas." (PMID 35955489, 2022). "Just like HJURP, increase H2Bub1 expression is also associated with luminal cancer, while significantly reduced H2Bub1 expression is present in basal type." (PMID 32257110, 2020). "Treatment of cancer cells with small interfering RNA (siRNA) against HJURP has caused abnormal chromosomal fusions and led to genomic instability, a common feature of human HCC." (PMID 26863619, 2016). "Overexpression and mis-localization of HJURP has been observed in lung cancer cell lines and these observations were linked with chromosomal instability and immortality of cancer cells." (PMID 21980305, 2011). "The importance of our results with SCM3/HJURP is further reinforced by the fact that HJURP overexpression has been observed in human cancer cells and is associated with chromosomal aberrations and aneuploidy." (PMID 21980305, 2011). "The role and underlying mechanisms of HJURP in various cancers." (PMID 37025176, 2023). "In this study, HJURP methylation was found to be strongly different in most tumors compared to normal tissue, and hypomethylation of HJURP was associated with poorer prognosis in various cancers." (PMID 36460821, 2022). "Therefore, the changes caused by the methylation status of HJURP in different cancers were assessed." (PMID 36460821, 2022). "Interestingly, although HJURP is frequently overexpressed in cancer, mutations in the HJURP gene have been identified which result in decreased levels of the protein and which are correlated with an increased risk of cancer." (PMID 30365520, 2018).
cancer (continued). "HJURP (Holiday Junction Recognizing Protein) located at chromosome 2q37 is a novel tumor suppressor shown to be an independent prognostic of death risk for cancer patients." (PMID 28410204, 2017). "We initially sought to understand what might cause the up-regulation of CENP-A and HJURP, frequently observed in human cancers." (PMID 28356341, 2017). "The elucidation of mechanisms underlying regulation of SCM3/HJURP in humans may help us identify and develop therapeutic targets for cancer therapy." (PMID 21980305, 2011). "HJURP encodes an indispensable factor for chromosomal stability in immortalized cancer cells." (PMID 20334636, 2010). "In addition, upregulation of HJURP was associated with poorer prognosis in a variety of cancers." (PMID 37025176, 2023). "However, in cancer cells, loss of HJURP results in higher ectopic CENP-A levels." (PMID 35235361, 2022). "We initially analyzed the expression levels of HJURP across a pan-cancer cohort using RNA-seq data from TCGA." (PMID 40290723, 2025). "In contrast, the upregulated gene set (e.g., SIM2, MYBL2, HJURP) was overexpressed in up to 22 cancers, indicating an oncogenic-like role and participation in common tumor-promoting pathways." (PMID 41439026, 2025). "Emerging evidence indicates that HJURP is frequently overexpressed in various types of cancer and plays a crucial oncogenic role in cancer progression." (PMID 40290723, 2025). "Among the biomolecules implicated in cancer epigenetics, DAXX, HJURP and CENPA represent three proteins heavily impacting oncogenesis in a variety of tumors." (PMID 39200236, 2024). "Subsequently pan-cancer analysis, we also revealed that high HJURP expression in 18 types of tumors, including LUAD (all p < 0.05)." (PMID 39649097, 2024). "While HJURP has indeed been reported in other types of cancers, its role in LUAD remains underexplored, which presents a significant opportunity for novel discoveries." (PMID 39649097, 2024). "In an in vivo model, overexpression of HJURP in most cancer cell lines promotes cell proliferation and invasiveness, reduces susceptibility to apoptosis, and promotes tumor growth." (PMID 37025176, 2023). "Various studies targeting HJURP as a prognostic and therapeutic target for cancer are gradually attracting interest and attention." (PMID 37025176, 2023). "Nevertheless, aberrations in DAXX and HJURP expression are consistently linked to patients’ DFS and OS for cancers originating from the brain, lungs, breast, esophagus, liver, prostate, ovaries, the uterus." (PMID 37958340, 2023). "Still, despite recent studies indicating that HJURP dysregulation contributes to the progression of a variety of human cancers, little is known about the specific mechanisms." (PMID 37025176, 2023). "In the available studies HJURP is upregulated in a variety of cancer tissues and cancer cell lines and is involved in tumor proliferation, invasion, metastasis and immune response." (PMID 37025176, 2023). "Based on PrognoScan and gene expression profiling interactive analysis (GEPIA), the elevated expression of HJURP worsened the survival time of individuals with cancer." (PMID 35274047, 2022). "HJURP is reported to be an oncogene that promotes cancer cell proliferation, migration, and invasion." (PMID 35873497, 2022). "Thanks to the rapid development of the information age, the functional role of HJURP in various cancers has been gradually revealed." (PMID 36460821, 2022). "The oncogenic effects of HJURP was mined in the entire TCGA pan-cancer database, as a result, compared with normal tissues, HJURP was significantly over-expressed in most types of tumor tissues (p < 0.001)." (PMID 36460821, 2022). "The datasets of Gene Expression Omnibus database along with The Cancer Genome Atlas project were used to evaluate the expression of HJURP in various types of tumors." (PMID 35274047, 2022).
cancer (continued). "HJURP has been demonstrated to participate in a number of biological processes including cell cycle across different cancers." (PMID 35274047, 2022). "We demonstrate that HJURP has an oncogenic influence on pan-cancer, and high HJURP expression worsens the survival of cancer patients." (PMID 35274047, 2022). "HJURP is overexpressed in a considerable number of cancers, and some changes in DNA methylation and genetic alterations are discovered in some types of tumors, such as kidney-related and adrenal gland-related tumors." (PMID 35274047, 2022). "At the same time, the results also showed that HJURP was related to tumor immune evasion through different mechanisms, including T cell rejection and methylation in different cancer types." (PMID 36460821, 2022). "A large number of studies have shown that HJURP exhibits a great potential in pan-cancer research, and the immune-related mechanisms have been clarified in some cancers." (PMID 36460821, 2022). "Our first pan-cancer study provides a relatively profound insights into the oncogenic roles of HJURP across different tumors." (PMID 35274047, 2022). "Like CENP-A, HJURP is overexpressed in certain cancers, including breast, liver, pancreatic, lung and melanoma cancers (The Human Protein Atlas), where upregulation of HJURP correlates with decreased survival." (PMID 32708729, 2020). "HJURP activation is a major event for maintaining chromosomal stability and thus support its induced expression in cancer cells undergoing frequent genomic instability." (PMID 32257110, 2020). "In cancer, HJURP has been reported to be highly expressed in some malignancies, including HCC, breast cancer, lung cancer, bladder cancer and glioma." (PMID 30111352, 2018). "Second, can mutations in CENP-A’s protein sequence, or in the gain or loss of specific post-translational modifications, alter its affinity for HJURP in cancer?" (PMID 29479426, 2018). "Among these, CENP-A and HJURP levels are elevated in human cancers, and both factors have been put forward as prognostic and predictive biomarkers." (PMID 28356341, 2017). "We thus propose that HJURP acts as a universal “navigator” that keeps the cancer cell on its path of hyperproliferation and potentiates further progressive changes associated with tumor development." (PMID 28356341, 2017). "HJURP was also recently identified as an independent biomarker of cancer outcome in luminal A patients." (PMID 27454576, 2016). "Consequently, the inhibition of HJURP attenuates the cancer cells' properties and increases the survival rate of patients, and thus, HJURP acts as a prognostic marker for several cancers." (PMID 41370334, 2025). "DAXX (Death Domain-Associated Protein), HJURP (Holliday Junction Recognition Protein) and CENPA (Centromere Protein A) proteins are implicated in epigenetic mechanisms, now in the spotlight of cancer research to better understand the molecular background of tumorigenesis." (PMID 39200236, 2024). "The activation of HJURP appears to play a pivotal role in the immortality of cancer cells." (PMID 39649097, 2024). "Further studies on its expression patterns, function, and molecular interactions in other cancer types should provide additional meaningful insights into the ubiquitous role of HJURP in cancer progression and help confirm its prognostic and therapeutic significance." (PMID 37025176, 2023). "Cell viability decreased in a dose-dependent manner and silencing HJURP could cause IC50 decline, which indicated that silencing HJURP probably enhanced sensitivity of cancer cells to AZD1775." (PMID 35173547, 2022).
cancer (continued). "In addition, this study also deeply explores the relationship between HJURP and tumor immune infiltration, and confirms that HJURP expression and immune infiltration characteristics can be used as the biomarkers for cancer detection and follow-up." (PMID 36460821, 2022). "We further investigated the prognostic value (OS and RFS) of HJURP for pan-cancer in TCGA." (PMID 35274047, 2022). "Altogether, our data show a new understanding of the nature of HJURP in cancer." (PMID 35274047, 2022). "Besides, the methylation of HJURP was inversely proportional to mRNA expression levels, which mediated the dysfunctional phenotypes of T cells and poor prognosis of different cancer types." (PMID 36460821, 2022). "At the same time, the oncogenic role of HJURP was mined in the entire TCGA pan-cancer database." (PMID 36460821, 2022). "HJURP is over‐expressed and related to the poor prognosis in some cancers." (PMID 35726713, 2022). "As many studies have suggested that HJURP is highly expressed in cancer, it may constitute a pivotal novel target or a biomarker for diagnosis." (PMID 35274047, 2022). "In addition to the genetic involvement in cancer development, HJURP also plays an epigenetic role in tumor progression." (PMID 36460821, 2022). "The molecular mechanism of how HJURP participated in cancer progression had various explanations." (PMID 35965590, 2022). "HJURP was abnormally expressed in most of the cancer types and subtypes in TCGA database." (PMID 36460821, 2022). "HJURP may serve as an oncogenic molecule, and its expression and immune infiltration characteristics can be used as a biomarker for cancer detection, prognosis, treatment design and follow-up." (PMID 36460821, 2022). "Elevated expression of HJURP has also been found in a variety of cancers." (PMID 34493071, 2021). "Similarly, in cancer cells overexpressing HJURP, 80% depletion of HJURP using siRNA, or complete knockout of HJURP using CRISPR/Cas9, induces cell cycle arrest and apoptosis, recapitulating the phenotype of CENP-A depletion in cancer cells." (PMID 32708729, 2020). "Efficient inhibition of HJURP is a possible subject for cancer research." (PMID 33114545, 2020). "The centromeric H3 variant CENPA and its cognate chaperone HJURP are overexpressed, usually in a mutually exclusive fashion, in several cancer types including lung, colon, prostate, breast, and brain tumors, where their overexpression correlates with poor prognosis." (PMID 33167489, 2020). "Consistently, high HJURP expression was observed in cancer tissues compared to normal tissues." (PMID 32439850, 2020). "First, can changes in HJURP expression observed in cancer result in ectopic deposition of CENP-A?" (PMID 29479426, 2018). "HJURP exhibits oncogenic activity in various cancer types including HCC." (PMID 30111352, 2018). "It has been reported that HJURP was markedly over-expressed in a broad range of human cancers." (PMID 26863619, 2016). "Another histone chaperone that is significantly overexpressed - actually the most frequently overexpressed chromatin factor in cancer - is HJURP, a chaperone of the histone H3 variant CENP-A, which facilitates aneuploidy and genome instability, another hallmark of cancer." (PMID 25484917, 2014). "We observed that HJURP is more highly expressed in cancer cells than in stroma cells." (PMID 25243117, 2014). "We might also speculate that the requirement of large amounts of HJURP is probably related to the genomic instability of cancer cells." (PMID 23638004, 2013).